CCND1 (cyclin D1)
Diseases named in the same sentence as CCND1 in open-access papers (continued):
Sharing a sentence is not in itself a finding about the gene and the disease.
ovarian carcinoma (continued). "We further analyzed the correlation between the expression rates of eIF4E and cyclin D1 proteins in ovarian cancer using Spearman's rank correlation test." (PMID 33489719, 2020). "The positive expression rate of eIF4E and cyclin D1 in ovarian cancer tissues was 68.3% (84/123) and 64.2% (79/123), respectively." (PMID 33489719, 2020). "CDK20 was also demonstrated to promote ovarian carcinoma cell proliferation via regulation of cyclin D1 and is a predictor of outcome in patients with ovarian carcinoma." (PMID 33198081, 2020). "Spearman's rank correlation test showed that there was a significant positive correlation between the eIF4E and cyclin D1 proteins in ovarian cancer." (PMID 33489719, 2020). "We further studied the correlation between the expression of eIF4E and cyclin D1 proteins and clinicopathological features of ovarian cancer, including age, clinical stage, lymph node metastasis status, and survival status by a univariate chi-squared test." (PMID 33489719, 2020). "A study of epithelial ovarian cancer observed that overexpression of CCND1 leads to stronger cell growth ability and less apoptosis." (PMID 32660514, 2020). "CCND1 expression is closely related to cell proliferation ability and apoptosis in epithelial ovarian cancer cells." (PMID 32660514, 2020). "We examined the cellular location and expression level of eIF4E and cyclin D1 proteins in ovarian cancer tissues by IHC." (PMID 33489719, 2020). "In the OVCAR5 ovarian cancer cell line, both 17β-estradiol and G1 stimulated proliferation, with an increase in cells in the S phase and the up-regulation of c-fos and cyclin D1." (PMID 32580290, 2020). "Downstream signaling processes that have been associated with the ERβ-mediated inhibition of growth in ovarian cancer cells include the decreased expression of pRb, phospho-AKT, cyclin D1 and cyclin A2 and increased expression of p21." (PMID 32580290, 2020). "In this concern, orthotopic ovarian cancer models respond better to olaparib treatment after knockdown of CCND1 gene compared with olaparib treatment alone." (PMID 33317149, 2020). "circANKRD12 silencing results in cyclin D1 down-regulation and subsequent invasion and reduction in proliferation in ovarian cancer SKOV3 cells." (PMID 31185953, 2019). "It has been demonstrated that miR-211 is downregulated in ovarian cancer, and restoration of miR-211 inhibits cell proliferation by suppressing cyclin D1 and CDK6 expression." (PMID 31235732, 2019). "We found that daidzein and ERB-041 decreased p-PI3K85, p-AKT, p-GSK3β, and cyclin D1 expression, suggesting PI3K/AKT/GSK3β/cyclin D1 signaling is linked to daidzein and ERB-041 induced G1 cycle arrest in ovarian cancer." (PMID 29743815, 2018). "This suggests that miR-519d has suppressive effects on ovarian carcinoma by downregulating RhoC, Bcl-2, cyclin D1, survivin, MMP2, MMP9, STAT3 and HuR expression." (PMID 28146423, 2017). "Our findings suggest that E2F1 functions as an oncogene in ovarian carcinoma in part by upregulating Bcl-2, cyclin D1, survivin, MMP2, and MMP9 expression." (PMID 28146423, 2017). "Western blot analyses demonstrated that both Cyclin‐D1 and C‐myc expression increased in mortalin‐overexpressing ovarian cancer cells (A2780‐O2 and A2780‐O8) compared with A2780‐AC, whereas Cyclin‐B1 levels decreased." (PMID 27374312, 2016).
ovarian carcinoma (continued). "In contrast, mortalin knockdown ovarian cancer cells showed increased Cyclin‐B1 levels and decreased Cyclin‐D1 and C‐myc levels." (PMID 27374312, 2016). "Cyclin D1 affects the epithelial-to-mesenchymal transition (EMT) in ovarian cancer stem cells, which is crucial in chemoresistance to therapy because of the ability of cells to contribute to cancer invasion and metastasis." (PMID 26207989, 2015). "Other pathways such as Lin28/Oct4 in ovarian cancer, carry Oct4 as a promotor bound to cyclin D1 (CCND1) protein." (PMID 26442212, 2015). "First, we observed that inactivating either of the two protein kinases was sufficient to reduce cyclin D1 protein levels in ovarian cancer cells, confirming that both MAP3K8 and p90RSK were required for cyclin D1 expression." (PMID 26456302, 2015). "Pak4 also induce ovarian cancer cell proliferation through the Pak4/c-Src/EGFR/cyclin D1/CDC25A pathway." (PMID 26218748, 2015). "Upregulation of Ccnd1 and loss of Cdkn2a in STOSE tumors is consistent with changes identified in human ovarian cancers by The Cancer Genome Atlas." (PMID 24672774, 2014). "The positive rates of cyclin D1 in well-, moderately- and poorly-differentiated ovarian carcinoma were 68.8, 70.0 and 90.0%, respectively." (PMID 24348821, 2014). "Ovarian carcinoma tissue with lymphatic metastasis showed a 90.9% prevalence of cyclin D1 expression and a 50.0% prevalence in metastasis-free ovarian carcinoma tissue." (PMID 24348821, 2014). "Cyclin D1 was predominantly located in the nuclei and cytoplasm of ovarian carcinoma cells, appearing as brown nuclei and dark brown sediments in the cytoplasm." (PMID 24348821, 2014). "As a result, Mirk kinase inhibition stabilizes cyclin D1 and cyclin D3 in ovarian cancer cells, as well as in several other types of cells." (PMID 25061503, 2014). "Entry into cycle, as shown by an increase in cyclin D1 levels, also occurred when quiescent ovarian cancer cells were treated for 24-98 hours with either of two Mirk kinase inhibitors, EHT5372 or EHT6840 (lower)." (PMID 25061503, 2014). "Cyclin D1, which controls the cell cycle, is the target gene of β-catenin and plays an important role in ovarian cancer." (PMID 25297608, 2014). "In ovarian cancer tissues, MMP-9 mRNA expression was significantly up-regulated and Cyclin D1 mRNA levels tended to increase in ovarian cancer tissues although these mRNA expression in each sample did not correlate with NIK mRNA expression." (PMID 24533079, 2014). "For example, KLF8 has been reported to transduce FAK to PI3K to AKT to SP1 signaling to up regulate cyclin D1 expression and enhance the cell cycle progression in ovarian cancer cell." (PMID 23722127, 2013). "In this study, suppressed cyclin D1 and E levels by EA treatment were observed in both ovarian carcinoma cells, indicating their possible role in EA-induced G1 phase arrest." (PMID 23843871, 2013). "Currently, cyclin D1 protein overexpression has been found in the majority of tumors (breast, gastric, esophageal and ovarian cancer, and B-cell lymphoma)." (PMID 22312289, 2012). "The expression of cyclin D1 protein in tumour sections from 81 patients with epithelial ovarian cancer was analysed using immunohistochemistry." (PMID 10584879, 1999). "In addition, when Cyclin D1 was overexpressed, we found that the apoptosis rate of ovarian cancer cells was reduced and the expression of MRP1 was increased." (PMID 39712859, 2025).
ovarian carcinoma (continued). "Flow cytometry results showed that compared with the ANXA114‐26 group, the apoptotic cells in the ANXA114‐26+OE‐Cyclin D1 group decreased, indicating that overexpression of Cyclin D1 could reverse the inhibitory effect of ANXA114‐26 on ovarian cancer cells." (PMID 39712859, 2025). "FSH, a physiological activator of ovarian functions, can promote the expression of progranulin in ovarian carcinoma cells, while progranulin can promote ovarian cancer cell proliferation, likely via activation of cyclin D1 and an increase in the proportion of cells in the S-phase of mitosis." (PMID 38575956, 2024). "Similarly, reduction of levels of the ribosomal protein RPS6 in ovarian cancer cells caused downregulation of CDK2, CDK4, CDK6, cyclin E, and cyclin D1, thereby blocking the transition from G0/G1 to S phase and suppressing cell proliferation." (PMID 38802745, 2024). "As shown in this study, HK2 overexpression could activate Wnt/β-catenin pathway by up-regulating β-catenin expression, further promoting cell proliferation and tumor formation by inducing c-myc and Cyclin D1 expression in ovarian cancer cells." (PMID 35711830, 2022). "A study suggested that RhoA/ROCK may be related to cyclin D1 levels in ovarian cancer, and our results also indicate that the level of RhoA may be affiliated with cyclin D1." (PMID 35725908, 2022). "Compound H42 inhibited ovarian cancer cell proliferation via HDAC6-mediated cyclin D1 degradation and suppressed ovarian cancer progression in nude xenograft mice, indicating compound H42 has a preclinical value in ovarian cancer therapeutics, warranting further investigation." (PMID 36467091, 2022). "For example, PKM2 promotes ovarian cancer growth though regulating CCND1 and CDKN1A expression." (PMID 35242214, 2022). "Moreover, the influence of CCND1 gene on the cell cycle and apoptosis rate of ovarian cancer cells were further analyzed by silencing." (PMID 34806539, 2021). "Furthermore, we also tested the expression of CCND1 in ovarian cancer tissues and corresponding normal tissues, indicating an upregulation of CCND1 in ovarian cancer." (PMID 34294689, 2021). "Our study further indicated that the combined inhibition targeting PSMC2 and CCND1 may be an effective treatment strategy for ovarian cancer." (PMID 34294689, 2021). "CCND1 gene is highly expressed in ovarian cancer tissue and related to prognosis." (PMID 34806539, 2021). "Moreover, GRP75-overexpression reduced Cyclin-B1 and upregulates Cyclin-D1 and c-myc to promote ovarian cancer cell growth." (PMID 34117210, 2021). "Therefore, the effect of silencing CCND1 gene on the apoptosis of ovarian cancer cells was evaluated." (PMID 34806539, 2021). "In summary, PSMC2 may promote the development of ovarian cancer through CCND1, which may predict poor prognosis of ovarian cancer patients." (PMID 34294689, 2021). "Bearing all these in mind, we hypothesized that CCND1 may serve as a potential downstream target of PSMC2 in the regulation of ovarian cancer." (PMID 34294689, 2021). "CCND1 gene amplification occurs in 20% of human ovarian cancer and squamous cell carcinoma." (PMID 34806539, 2021). "Thus, OS and PFS of ovarian cancer patients with high CCND1 expression were significantly shorter than those of patients with low CCND1 expression (P < 0.05)." (PMID 34806539, 2021). "Altogether, we believe that PSMC2 may regulate the development of ovarian cancer in combination of CCND1." (PMID 34294689, 2021). "Until now, there are few studies on the expression of CCND1 gene in ovarian cancer, and its role and function remain unclear." (PMID 34806539, 2021). "Therefore, there was significant difference in the expression of CCND1 gene between ovarian cancer and normal ovarian tissue, which was highly expressed in ovarian cancer tissue." (PMID 34806539, 2021). "Furthermore, it has been documented that cells in breast and ovarian cancers often coexpress p21 and cyclin D1 genes, resulting in growth arrest." (PMID 34903946, 2021).
ovarian carcinoma (continued). "The LPA2 receptor induces the expression of VEGF by participating in the production of IL8 and induces the expression of cyclin D1 through transcriptional activation, thereby stimulating the growth of ovarian cancer and enhancing the invasiveness of ovarian cancer 51,52,55,56." (PMID 32284748, 2020). "And positive staining of cyclin D1 was identified in the cell cytoplasm of ovarian cancer tissues." (PMID 33489719, 2020). "Moreover, genistein, daidzein and ERB-041 treatment reduced p-FAK, p-PI3K, p-AKT, p-GSK3β, p21 or cyclin D1 expression in ovarian cancer cells." (PMID 29743815, 2018). "In our study, mutational analysis of TCGA ovarian cancer data has shown that a significant percentage of patients have mutations or dysregulated expression of CDKN2A, CDK4, CDK6, or CCND1 that would likely make them good candidates for CDK4/6 inhibitor therapy." (PMID 29644000, 2018). "To determine whether cell cycle was a contributing factor to cell growth promotion, we investigated the involvement of cyclin D1 (a member of the cyclin protein family) in the S1P-induced increase in ovarian cancer cell proliferation." (PMID 28460443, 2017). "Moreover, it has been reported that breast as well as ovarian cancers often had cells that co-expressed the p21 and cyclin D1 genes, often leading to growth arrest." (PMID 28797035, 2017). "Western blot showed that miR-519d transfection in ovarian carcinoma cells downregulated RhoC (Ras homolog gene family member C), Bcl-2, cyclin D1, survivin, MMP2, MMP9, STAT3 (signal transducer and activator of transcription 3), and HuR (ELAV-like RNA-binding protein 1) expression (P < 0.05)." (PMID 28146423, 2017). "Everolimus decreased expression of CDK6 and cyclin D1 and increased expression of p21 in both cell lines after 24 hours of treatment, suggesting that everolimus induces growth inhibition through induction of G1 phase arrest in ovarian cancer cells." (PMID 26959121, 2016). "Differential cyclin D1 expression, a protein essential for the G1 to S progression of the cell cycle, plays a crucial role in malignant diseases; and cyclin D1 overexpression has been reported in ovarian cancer." (PMID 26207989, 2015). "In addition, we observed that miR-634 overexpression in ovarian cancer cell lines and patient samples negatively regulates important cell-cycle genes (CCND1) and Ras-MAPK pathway components (GRB2, ERK2, RSK1 and RSK2)." (PMID 26576679, 2015). "Additionally, the expression of miR-572 correlated inversely with the protein expression levels of SOCS1, p21 and positively with Cyclin D1 in ovarian carcinoma specimens." (PMID 25893382, 2015). "In the present study, immunohistochemistry S-P assays were used to detect the expression of cyclin D1 in ovarian carcinoma tissues and found an increasing trend in the positive staining rates of NOT, OSA, OS-BT and OSC samples from 10.0, 25.0, 55.6 to 73.9%, respectively." (PMID 24348821, 2014). "The results implied that the secreted IL-21 from hUCMSCs-LV-IL-21 may assist in the inhibition of ovarian cancer growth in the mouse model by down-regulation of β-catenin and cyclin-D1 expression in Wnt/β-catenin signal transduction pathway." (PMID 24444073, 2014). "The down regulation of β-catenin and cyclin-D1 in the tumor tissues may refer to the inhibition of SKOV3 ovarian cancer growth in mice." (PMID 24444073, 2014). "The TCGA array dataset was analyzed by the Cancer Genome Research Analysis Network and two of the top gene changes in the STOSE cell microarray were among those reported in the pathways most frequently altered in ovarian carcinomas: downregulation of Cdkn2a (−5.8) and overexpression of Ccnd1 (+6.2)." (PMID 24672774, 2014). "Interestingly, Cdkn2a is down-regulated in 30% of HGSC cases and Ccnd1 is amplified in 4% of the cases, according to TCGA ovarian carcinoma array." (PMID 24672774, 2014). "Both EA-treated ovarian carcinoma cells possessed decreasing levels of cyclin D1, E, and B1." (PMID 23843871, 2013).
ovarian carcinoma (continued). "In this study, we hypothesized that the addition of COX inhibitors could enhance the antitumor effect of taxol on xenograft ovarian cancer by reducing the expression of cyclin D1 and decreasing cell proliferation." (PMID 22949827, 2012). "As expected, our data clearly showed that the expressions of both Cyclin-D1 and C-myc were upregulated by PITX2even in tumor tissues obtained from tumor xenograft mice, whereasPITX2 depleted ovarian cancer cells exhibited reduction in the expressions of Cyclin-D1 and C-myc." (PMID 22615897, 2012). "In this study, we have demonstrated that 25HC is able 1) to activate ERα, possibly by binding directly as an agonistic ligand, 2) to up-regulate diverse estrogen target genes, 3) to modulate ERα and Cyclin D1 protein levels and 4) to stimulate growth effects in breast and ovarian cancer cells." (PMID 21304949, 2011). "Downregulation of cyclin D1 expression via a COX-2 dependent mechanism by Celecoxib could be a potential in vivo mechanism to inhibit ovarian cancer growth." (PMID 21152316, 2010). "The expression of cyclin D1 might be responsible for progression and/or ultimately tumorigenesis of human ovarian cancer epithelial tissues." (PMID 21152316, 2010). "Targeting cyclin D1 may be one of the molecular mechanisms restraining the growth of ovarian cancer by COX-2 inhibition." (PMID 21152316, 2010). "Our results suggest that the antitumor efficacy of Celecoxib against ovarian cancer in mice may in part be mediated through suppression of cyclin D1, which may contribute to its ability to suppress proliferation." (PMID 21152316, 2010). "Our results showed that the expression levels of Cyclin D1 and NF‐ĸBp65 in SKOV3/DDP cell line were higher than those in SKOV3 cell line, suggesting that the elevated expression of Cyclin D1 and NF‐ĸBp65 may be related to drug resistance in ovarian cancer cells." (PMID 39712859, 2025). "TNKS inhibition or knockdown reduced ovarian cancer cell proliferation, colony formation, migration, invasion, and tumorigenic potential in nude mice, and these changes correlated with the downregulation of targets (cyclin D1, MDR, and MMP‐9) of Wnt/β‐catenin signalling." (PMID 38898581, 2024). "A recent study has identified that MYC, EGFR, and CCND1 can be amplified on extrachromosomal DNA (ecDNA) in different tumor cell lines, which may provide novel insight into identification of the mechanism of ovarian cancer progression." (PMID 35739532, 2022). "Therefore, it was speculated that MYC, EGFR, and CCND1 might affect the survival of ovarian cancer patients by mediating chemoresistance-related pathways." (PMID 35739532, 2022). "Additionally, we observed that protein expression of MYC, EGFR, and CCND1 was notably increased in cancer tissues of ovarian cancer patients based on data from Human Protein Atlas, suggesting their important functional significance in ovarian cancer." (PMID 35739532, 2022). "Thus, DLGAP5 knockdown could attenuate cell growth and induce apoptosis via cyclin-dependent kinase 1/cyclin D1/Bcl-2 signaling in ovarian cancer cells." (PMID 36499051, 2022). "Therefore, we speculated that MYC, EGFR, and CCND1 might enhance resistance to platinum chemotherapy in ovarian cancer." (PMID 35739532, 2022). "Moreover, preliminary mechanistic study revealed that PSMC2 may execute its regulatory effects on ovarian cancer in combination with CCND1." (PMID 34294689, 2021). "Moreover, considering that CCND1 plays essential roles in current therapeutic strategies for ovarian cancer patients that involve platinum therapy and checkpoint inhibitors, the exploration of the functions of PSMC2 and CCND1 in ovarian cancer should be of great significance." (PMID 34294689, 2021). "The mechanism of CCND1 gene in ovarian cancer remains unclear." (PMID 34806539, 2021). "Thus, CCND1 gene may affect the prognosis of ovarian cancer patients, which is consistent with the results of previous studies." (PMID 34806539, 2021).